VTN (vitronectin)
Diseases named in the same sentence as VTN in open-access papers (continued):
Sharing a sentence is not in itself a finding about the gene and the disease.
cancer (continued). "PAI-1 inhibited the motility of vascular smooth-muscle cells, human amnion WISH cells, and carcinoma cells via interaction with vitronectin, and vitronectin blocked the LRP1/PAI-1 pathway." (PMID 22747686, 2012). "This supports the model that vitronectin incorporation into the sites of injured, stressed, and, possibly, also cancer tissue is at least partially dependent on the interactions with a cytoplasmic component exposed after tissue injury." (PMID 21573223, 2011). "High-molecular-weight-kininogen, apolipoprotein A1, soluble vascular cell adhesion molecule-1, plasminogen activator inhibitor-1, vitamin-D binding protein and vitronectin were decreased in the cancer group." (PMID 19400944, 2009). "On the other hand, vitronectin, a secreted glycoprotein that is abundantly found in plasma and has multifunctional roles involved in cell adhesion, migration and cancer processes, was significantly higher in DTC compared to FA patients’ microvesicles, but its levels were highest in HCs." (PMID 41193833, 2025). "Moreover, increased vitronectin levels have been described in the plasma of patients with different cancers." (PMID 39201421, 2024). "Furthermore, NF-κB regulates cancer cell invasion by controlling the expression of adhesion molecules such as fibronectin and vitronectin, which influence MMP-2 and MMP-9 activity." (PMID 39684484, 2024). "In addition, PAI-1 stimulation leads to blockage of αvβ3-mediated cell migration on vitronectin and of tumoral extracellular matrix remodeling, which support the cancer cell migration in several types of cancers, including CRC." (PMID 37760840, 2023). "Additionally, increased vitronectin synthesis and elevated levels of integrin β5 correlate with disease progression of different types of cancer, including colorectal, brain, breast and non-small cell lung cancer." (PMID 35532004, 2022). "In conclusion, integrin β5 promotes cancer cell proliferation by mediating adhesion to vitronectin." (PMID 35532004, 2022). "Studies of the ovarian cancer TME have identified vitronectin and fibronectin as key facilitators of cancer cell attachment to the mesothelium that lines peritoneal organs, indicating these mechanisms may be important in peritoneal cancers as well." (PMID 36465383, 2022). "Ultimately, our data indicated that ECM components such as Fibronectin and Vitronectin might modulate cancer cell behavior towards tensional homeostasis." (PMID 35681670, 2022). "These interactions between CAFs and cancer cells were filtered, and a high-resolution map with the most relevant interactions of the PI3K-AKT pathway revealed the involvement of collagens, fibronectin, vitronectin, laminin, and osteopontin from CAFs with integrins in cancer cells." (PMID 36352420, 2022). "For instance, does sMAC containing vitronectin mediate unknown complement functions or contribute to hematological or cancer-related functions?" (PMID 33240274, 2020). "Finally, vitronectin, which, along with osteopontin, is a potent ligand of αvβ3 integrin, seems to modulate cancer cell adhesion, migration, and angiogenesis." (PMID 32340328, 2020). "Dendron‐coated liposomes were found to interact with specific proteins of the blood serum and plasma proteins such as vitronectin and ApoH, which could promote uptake into cancer and mesenchymal stem cells." (PMID 31943635, 2020). "Interaction between vitronectin and Integrin αvβ3, also known as the vitronectin receptor, could be key to understanding vitronectin’s role in cancer." (PMID 33211735, 2020). "Besides of ability to affect cancer cell adhesion, motility and invasion, VTN also assists cancer cells to resist the cell death induced by apoptotic induction." (PMID 30819137, 2019).
cancer (continued). "These cancer-upregulated integrins bind to specific extracellular matrix protein ligands, such as vitronectin, fibronectin, laminin, and collagens, that are deposited in the cancer microenvironment, thereby promoting the metastatic dissemination of primary cancer cells to distant organs." (PMID 30658425, 2019). "Finally, vitronectin is not only a ligand for pro-adhesive integrins on the surface of cancer cells but is also a very potent chemokinetic factor." (PMID 27634880, 2016). "Membrane-type 1 MMP (MT1-MMP or MMP-14), which is expressed on the cell membrane, promotes the invasion of cancer cells by directly degrading extracellular matrix components, including fibronectin, vitronectin, laminin-1 and -5, fibrin, proteoglycans and collagen types I, II and III." (PMID 24527093, 2014). "Interestingly, whereas EGF-induced carcinoma cell migration on vitronectin is sensitive to Src inhibition as expected, cell migration driven by the MUC1 cytoplasmic domain does not require Src kinase activity." (PMID 22586492, 2012). "As such, αvβ5-mediated carcinoma cell migration on a vitronectin substrate in vitro may represent a surrogate assay for metastasis in vivo." (PMID 22586492, 2012). "HMWK, ApoA1, PAI-1, VDBP and vitronectin levels were significantly decreased in cancer patients." (PMID 19400944, 2009). "Furthermore, Fibronectin and Vitronectin might modulate cancer cell behavior towards tensional homeostasis." (PMID 35681670, 2022). "We also provided evidence that vitronectin not only plays a role in cell adhesion but is a very potent chemokinetic factor that, if freed from the chaperone complex with fibrinogen, increases the migration of cancer cells to a much higher degree than other known chemoattractants." (PMID 27634880, 2016). "Mechanistically, VTN upregulates SLC6A8 expression in CRC cells and macrophages by enhancing FAK phosphorylation, which increases creatine and ATP uptake, promoting cancer progression and macrophage polarization." (PMID 40538300, 2025). "In fact, it has been previously reported, that αvβ6 is capable of promoting cancer cell migration upon binding to and adhering to protein ligands of the ECM, such as fibronectin and vitronectin." (PMID 38890650, 2024). "These cancer cells express αvβ3, an integrin receptor for various extracellular matrix proteins (ECM), such as vitronectin and fibronectin (the binding between αvβ3/ECM through the ECM RGD domain)." (PMID 38535808, 2024). "In an ovarian metastasis model, ECM components such as fibronectin, vitronectin and collagen I were cleaved into small fragments by activated MMP-2 and facilitate cancer cell adhesion and invasion by binding to integrin receptors." (PMID 36639546, 2023). "Integrins mediate the communication between ECM and cancer cells through binding to ECM proteins, such as FN and vitronectin (VN)." (PMID 37823053, 2023). "Therefore, FN1 and VTN might also be translatable to other cancer types or disease settings." (PMID 35477343, 2022). "The antibody on the beads of the Bio‐Plex Pro Human Cancer Biomarker Panel 2 in this study is an anti‐total PAI‐1 antibody, which measures the sum of the active type, latent type, vitronectin complex, tissue‐type plasminogen activator complex, and uPA complex." (PMID 33088925, 2020). "As expected, cancer cluster-related genes ATF3, PDZK1, VTN and CXCL8 were highly expressed in CDRCC tissues, and patients with high expression of these genes had significantly poor prognosis (P<0.01)." (PMID 33162821, 2020). "PAI-1 can exist as tPA-PAI-1, uPA-PAI-1, vitronectin-PAI-1, and LPR1-PAI-1 complexes, which are closely related to the function of PAI-1 in cancers." (PMID 33371368, 2020). "We measured adhesion of MDA-MB-231 and MCF-7 cancer cells to well plates coated with purified ECM components (collagen I, collagen II, collagen IV, vitronectin, fibronectin, laminin, and tenascin)." (PMID 26816215, 2016).
cancer (continued). "We treated MDA-MB-231 cancer cells with LPA and allowed them to bind one of four different ECMs (collagen I, collagen IV, laminin and vitronectin)." (PMID 26816215, 2016). "Vitronectin (VTN) is a multifunctional glycoprotein in blood and the extracellular, which could be an effective biomarker for many cancers." (PMID 39717749, 2024). "Because uPA binding to the uPA receptor increases the binding affinity of vitronectin to the uPA receptor, a blockade of PAI-1 can reduce cancer cell migration, proliferation, and survival by increasing cell adhesion to the ECM through the promotion of uPA receptor binding to vitronectin." (PMID 34202399, 2021). "Together, these results demonstrate that the MUC1 intracellular domain is both necessary for EGF-induced carcinoma cell migration on vitronectin and sufficient to drive cell migration on vitronectin and metastasis in the absence of EGF." (PMID 22586492, 2012). "This novel observation may explain the preferential metastasis of cancer cells to lymph or body cavities where the concentration of fibrinogen is relatively low, and thus vitronectin is not bound to fibrinogen and as free protein can chemoattract cancer cells." (PMID 30375490, 2018). "Not surprisingly, similarity among different cancer types was identified in only 6 out of 23 clusters, including E3 (IRS2, KRT6A), E5 (CD24, STMN1), E8 (GKN1, MUC5AC), E9 (PHGR1, TFF3), E10 (TFF3, TPO) and E13 (VTN and ITIH5)." (PMID 36333338, 2022).
infection (30 papers, 2010 to 2025). The state of being infected such as from the introduction of a foreign agent such as serum, vaccine, antigenic substance or organism. "The BCAM0223::Tp mutant is deficient in hemagglutination, affected in adherence to vitronectin and in biofilm formation and showed attenuated virulence in the Galleria mellonella model of infection." (PMID 22848588, 2012). "To investigate the impact of VTN on CRC cells, we constructed VTN‐silenced CAFs by lentiviral infection." (PMID 40538300, 2025). "Emp is a secreted adhesin that binds to the host cell proteins fibronectin, fibrinogen, collagen and vitronectin and Sbi has been shown to be involved in immune evasion and play a role in later stages of the infection." (PMID 39203567, 2024). "For example, its surface proteins E and F can bind to complement regulatory factor vitronectin and contribute to bacterial colonisation and infection." (PMID 39407352, 2024). "Another property of vitronectin that makes it indispensable for maintaining airway health is its inhibitory ability of MAC formation that confers protection to host cells during infection." (PMID 25768308, 2015). "Subsequently, we tested if in our model PAI-1 would bind to vitronectin, since this binding is associated with increased/prolonged PAI-1 activity, and if this interaction is altered during infection." (PMID 25852676, 2015). "Within 3 weeks of infection, we identified colonies that resembled human ESCs using mTeSR1 and Matrigel or vitronectin." (PMID 24824994, 2014). "Cells expressing recombinant αvβ3 or αIIbβ3 facilitate infection by SNV, NY-1V, ANDV, and HTNV, and infection is blocked by antibodies to β3 integrins and by the β3 integrin ligand vitronectin." (PMID 22811711, 2012). "Moreover, a supervised analysis based on a decision-tree recognised three proteins (Fetuin-A, Ig lambda-2chain-C-region, Vitronectin) that are able to robustly discriminate between the two classes independently from the infection stage." (PMID 36834989, 2023). "In the later stage of infection, focal adhesion pathway was associated with ECM receptor interaction pathway through SPP1, col6a2, COL3A1 and VTN proteins, while focal adhesion pathway linked with leukocyte transendothelial migration pathway by RAC1 and LOC733637." (PMID 32632500, 2020). "Patients with polymicrobial infections exhibited some of the highest vitronectin levels." (PMID 30061873, 2018). "Vitronectin and laminin 511 inhibited HAdV-37 infection by approximately 65% and 55%, respectively." (PMID 27974569, 2017). "However, spore adherence decreased to 61% upon treatment of spores with 25 μg/ml of vitronectin prior to infection." (PMID 27713865, 2016). "A reduced level of vitronectin in the airways may compromise the host’s ability to fight infection, because of the intrinsic antimicrobial and immune-cell-recruiting properties of the glycoprotein." (PMID 25768308, 2015). "In addition, to evaluate the role of vitronectin during infection, we have also used capsulate isolates of a serogroup B strain MC58 representing a phenotype that may be isolated from the blood (replete with capsule, pili, Opa and Opc)." (PMID 20502634, 2010). "Infection with A7UF also enhanced AoSMC migration before and after the addition of the agonist vitronectin." (PMID 36483452, 2022). "We contend that the repeated presentation of vitronectin-bound-SE36, as a result of infection, was exploited by the parasite such that SE36 disguises itself as a host antigen, avoiding clearance by phagocytosis and leading to the gradual acquisition of immune tolerance." (PMID 36590593, 2022). "Further, there was no obvious difference in expression of vitronectin before or after NTHi infection." (PMID 26572616, 2015). "Also, pre-incubation of HT-29 cells with vitronectin or fibronectin (RGD-containing integrin ligands) did not affect HAdV-41 infection." (PMID 29968781, 2018).
infection (continued). "Preincubation of HCE cells with either vitronectin or laminin 511 inhibited HAdV-37 infection by 50%, thus providing additional support for the suggestion that interactions between the HAdV-37 penton base and RGD-binding integrins are necessary for efficient infection of corneal cells." (PMID 27974569, 2017). "In particular, some genes involved in immune/inflammatory responses and infection (e.g., IL19, MAPK15, and SERPINB10) and components of a complement system (e.g., C4B, VTN, BDKRB1, and C4BPA) have not been previously reported regarding their expression and functions in human omental adipose tissue." (PMID 30816281, 2019). "Interestingly, we have identified elevated serum levels of NEB, VTN, and TTN in SVM patients, while in non-severe infection, serum levels of these candidates were found to be nearly similar compared to the healthy controls." (PMID 27090372, 2016). "Fibronectin and vitronectin reproducibly inhibited infection in these experiments by up to 40%, whilst LAMB1, ICAM-1, VCAM-1 or heparan sulphate did not affect the efficiency of infection." (PMID 21573183, 2011).
bacterial infection (2 papers, 2021 to 2025). "This phenomenon is observed in heparin-binding peptides derived from laminin, vitronectin and fibronectin, which exert a direct inhibitory effect on bacterial infection." (PMID 34515624, 2021).
CNS tumors (2 papers, 2021 to 2023). "Mao-Hua Chen demonstrated through ROC curve analysis that serum vitronectin levels discriminated LGG significantly from HGG from healthy volunteers and other CNS tumors (AUC 0.995, 0.993, and 0.996, respectively)." (PMID 37704931, 2023).
neurodegenerative disease (2 papers, 2022). A disorder of the central nervous system characterized by gradual and progressive loss of neural tissue and neurologic function. "This review summarizes the functions of VTN and its receptors in neurons and describes the role of VTN in the blood–brain barrier and neurodegenerative diseases." (PMID 36293243, 2022). "On the other hand, VTN and its receptors can influence the phagocytosis of microglia and play a role in neurodegenerative diseases such as AD and AMD." (PMID 36293243, 2022). "Dysfunction and misfolding of VTN can lead to the pathology of neurodegenerative diseases and BBB leakage." (PMID 36293243, 2022). "There is increasing evidence that VTN plays a role in the pathologies of neurodegenerative diseases." (PMID 36293243, 2022). "The mechanism as to how VTN affects neuron activity may help to further clarify the pathogenesis of neurodegenerative diseases and facilitate the diagnosis and treatment of these diseases." (PMID 36293243, 2022). "A recent preprint suggests that SARS-CoV-2 induces amyloid aggregation of several proteins involved in neurodegenerative diseases such as APLP1, ApoE, clusterin, α2-macroglobulin, PGK-1, ceruloplasmin, nucleolin, 14–3-3, transthyretin, and vitronectin." (PMID 36362302, 2022).
neurological diseases (2 papers, 2014 to 2022). "Recent evidence, however, suggests a broader role for VTN in neurological diseases." (PMID 36293243, 2022). "Recently, VTN was reported to play an essential role in regulating neuronal activities and functions, while there is still a lack of research on its role in neurological diseases." (PMID 36293243, 2022).
cardiovascular disease (1 paper, 2025). "For example, vitronectin (P04004) has already attracted considerable interest as a putative biomarker for cardiovascular disease." (PMID 41361833, 2025).
heart disease (1 paper, 2022). "Also in cluster 4 were Cystatin-3 (CST3) and Vitronectin (VTN), proteolysis inhibitors which have been described as robust biomarkers of heart disease." (PMID 34741130, 2022).
Metabolic disorders (1 paper, 2017). "Metabolic disorders further impacted cell death and metastasis, in part by regulating FN1, VTN, ENO2, and VEGFA." (PMID 28211215, 2017).
retinopathy (1 paper, 2022). "In line with this, Basu and colleagues observed in oxygen-induced murine retinopathy that the role of PAI-1 in retinal angiogenesis is enhanced by the presence of vitronectin in regions where new vessels form." (PMID 35681461, 2022).
vascular disorder (1 paper, 2023). A general term used to describe any disease affecting blood vessels]. "PAI1 not only functions as a plasminogen activator inhibitor, but also interacts with vitronectin to promote the development of multiple cancers, thrombotic and vascular disorders." (PMID 37542348, 2023).
VTN also shares sentences with these, for which no sentence is quoted: colitis (3 papers); macular degeneration (3); systemic lupus erythematosus (3); type 2 diabetes mellitus (3); viral infections (2); acute coronary syndrome (1); acute kidney injury (1); adenocarcinoma (1); Arthritis (1); bladder cancer (1); brain hemorrhage (1); cardiac hypertrophy (1); cataract (1); chronic obstructive pulmonary disease (1); colon (1); connective tissue disorder (1); ductal adenocarcinomas of the pancreas (1); Endotoxemia (1); epithelioid hemangioma (1); esophageal squamous cell carcinoma (1); exfoliation glaucoma (1); gastric adenocarcinoma (1); glomerular diseases (1); glomerulonephritis (1); head and neck cancer (1); infarction (1); Infertility (1); Kaposi's sarcoma (1); kidney (1); lung adenocarcinoma (1).
A further 17 diseases each share a sentence with VTN in 1 paper.